TNF (tumor necrosis factor)
Diseases named in the same sentence as TNF in open-access papers (continued):
Sharing a sentence is not in itself a finding about the gene and the disease.
diabetes (continued). "Diabetes is associated with an increase in plasma TNF, IL-1β, interleukin 6 (IL-6), interferon-g (IFNγ), and PAI-1, as well as alteration in immune cell response leading to chronic low-grade inflammation." (PMID 34054705, 2021). "Of note, the NF-κB regulated TNF receptor, TNFR2, was upregulated under diabetes mellitus, suggesting the association of NF-κB signaling with the autocrine effects of TNF-α on microglia." (PMID 34434927, 2021). "Our results confirm that there is a high correlation between leptin, TNF-α, and insulin and these correlations cause many disorders in people with diabetes." (PMID 34039404, 2021). "In pathological conditions, eNOS expression decreases in response to inflammatory and metabolic stimuli such as tumor necrosis factor (TNF) or diabetes-associated advanced glycation end-products." (PMID 34026871, 2021). "A study reported that the salivary TNF–α levels were significantly higher in subjects with type 2 diabetes mellitus when compared with healthy controls suggesting that diabetes mellitus is associated with increased salivary TNF-α levels." (PMID 33676486, 2021). "Increased levels of cyclooxygenase-2 (cox-2), interleukin–6 (IL-6), and tumour necrosis factor-alpha (TNF-α) are associated with the inflammatory response and in diabetes, and increased levels of these contribute to chronic wounds that do not heal." (PMID 33628374, 2021). "The study showed that Dicer, numerous miRNAs and inflammatory cytokines (TNFα and cardiac IL-10) are associated with diabetes-induced HF." (PMID 33639953, 2021). "A recent systematic review and meta-analysis investigated the association between TNF-alpha and type 2 diabetes mellitus and concluded that there is considerable heterogeneity between studies and further work is needed." (PMID 32089876, 2020). "Diabetes is associated with an increase in inflammatory cytokines, such as tumor necrosis factor and interleukin 6 have detrimental effects on muscle mass, strength, and physical performance in older adults." (PMID 33076841, 2020). "Specific inhibitor or genetic deficiency of TNF-α greatly reduced the leukocyte adhesion and blood-retinal barrier breakdown in the diabetic retina." (PMID 32019593, 2020). "It has been well documented that the appearance of peripheral neuropathy in type 1 and type 2 diabetes mellitus is strongly associated with increases in inflammatory biomarkers, including C-reactive protein, TNF-α, and IL-6." (PMID 32973438, 2020). "OP exposure indicated risk of diabetes and insulin, glycaemia, adiponectin, triglycerides, and TNF-α dysregulations." (PMID 33194944, 2020). "Other effects of hesperidin treatment in diabetic animals include a reduction in inflammatory parameters, such as tumor necrosis factor alpha (TNFα), interleukin (IL)-6 or IL-1β, and the reduction of oxidative stress associated with diabetes." (PMID 32443766, 2020). "An animal study showed that long-term zeaxanthin treatment decreases the levels of IL-6, IL-1β, and TNF-α and ameliorates diabetes-associated anxiety and depression in diabetic rats." (PMID 31215856, 2020). "TNF-α is also implicated in the development of diabetes mellitus and inflammatory polyarthropathies." (PMID 32793203, 2020). "Inflammatory cytokines, including TNF-α and IL-6 are associated with diabetes and are linked to increased macro-vascular disorders." (PMID 33680027, 2020). "We have previously reported that diabetes-induced increases in tumor necrosis factor alpha (TNFα) can cause phosphorylation of insulin receptor substrate 1 (IRS-1) on serine 307, thus inhibiting normal insulin signal transduction in retinal endothelial cells." (PMID 32432228, 2020). "It has been previously demonstrated that both estrogen deficiency and diabetes increased the bone expression of TNF-α mRNA in mice; the effect observed in diabetic mice was strongly intensified by estrogen deficiency." (PMID 33204216, 2020).
diabetes (continued). "The mouse studies indicated possible roles of renin-angiotensin and kallikrein-kinin systems and increased expression of TNF-α in the development of osteoporotic changes induced by diabetes and estrogen deficiency." (PMID 33204216, 2020). "The C3 knockout in the present study also caused a decrease in the expression of inflammatory factors, such as IL‐6 and TNF‐α, thereby reducing inflammation caused by diabetes." (PMID 32794619, 2020). "Upon infiltrating into the islet, the immune cells secrete a variety of pro-inflammatory cytokines, such as IL-1β, tumor necrosis factor alpha (TNF-α), and γ-interferon, and cause islet cell function defects and diabetes." (PMID 31024619, 2019). "In this study, a significantly reduced risk of diabetes was found in RA patients treated with TNF inhibitors when adjusting for covariates such as disease activity and BMI." (PMID 30673733, 2019). "The inflammatory process in diabetes is associated with the secretion of inflammatory cytokines by endothelial cells, e.g., tumor necrosis factor alpha (TNFα) and interleukin 6 (IL-6), and with the reduction of cell proliferation." (PMID 30610442, 2019). "TNF-α and IL-1β play a pathogenic role in DR since they contribute to diabetes-induced degeneration of retinal capillaries." (PMID 31921199, 2019). "In the covariate models, higher age was associated with increased TNF-α and IL-6, and presence of diabetes with higher concentrations of TNF-α, IL-6, and IL-10." (PMID 31755034, 2019). "Prolonged exposure to pro-inflammatory cytokines, particularly the combination of IL-1β and TNFα, induced pancreatic beta cell apoptosis, which is one of the major causes of islet inflammation during the development of diabetes." (PMID 31728004, 2019). "In multivariate Cox regression models adjusting for continuous propensity scores, exposure to TNF inhibitors was associated with reduced incidence of diabetes, with a hazard ratio of 0.35 (95% CI 0.13, 0.91, p-value 0.03)." (PMID 30673733, 2019). "Another study found that the testosterone treatment led to the suppression of TNF, IL-1, and IL-6 released from cultured peripheral blood monocytes isolated from type 2 diabetes mellitus men with an androgen deficiency." (PMID 31500378, 2019). "Evidence for a causal role of TNF-α in diabetic heart failure has been provided in a rat model of streptozotocin-induced diabetes mellitus." (PMID 31064116, 2019). "Other studies have shown that pro-inflammatory cytokines (e.g., IL-6 and TNF-α) are involved in brain dysfunction caused by diabetes." (PMID 31197747, 2019). "The lower hazard ratio for diabetes observed in patients receiving TNF inhibitors in our study underline that choice of RA treatment can have broad implications for the patient." (PMID 30673733, 2019). "Existing clinical data indicate that diabetes, as a whole, is strongly associated with elevated levels of IL-6, TNF-α, CRP, and adiponectin in Mexican Americans." (PMID 30868076, 2019). "Contrary to the protective effect of TNF inhibitors, glucocorticoid use was associated with a significant increase in risk of diabetes in our data, especially in patients prescribed doses of 7.5 mg daily or more." (PMID 30673733, 2019). "IL-6 and TNF-α, as major inflammatory factors, participate in the development of T2DM; the increasing expression of TNF-α and IL-6 can cause pathological injury and diabetes complications." (PMID 30544624, 2018). "The precise mechanism underlying the TNF–TNFR pathway in patients with diabetes requires further investigation." (PMID 30333553, 2018). "Several studies have shown a relationship between polymorphisms in the TNFα region (308-) and an increased susceptibility to various pathologies, including diabetes, coronary disease, retinopathy or polycystic ovarian syndrome." (PMID 30386510, 2018). "In mice, TNF-α and PA were administered to mimic risk factors during pre-diabetes and insulin-stimulated 18F-FDG uptake in the heart was evaluated by PET." (PMID 28304381, 2017).
diabetes (continued). "The ameliorative effect of simvastatin on diabetes-associated inflammation was explored via determination of serum TNF-α and CRP levels and cardiac NF-κB expression." (PMID 29138670, 2017). "Last, levels of inflammatory cytokines IL-1β and TNF-α and anti-inflammatory cytokine IL-10 were detected in the plasma, since inflammation is a key pathogenic factor for diabetes consequence." (PMID 29296174, 2017). "Hyperglycemia and oxidative stress associated with diabetes sustain prolonged influx of inflammatory cells through inducing excessive proinflammatory cytokines (IL-1β, TNF-α, etc.)production." (PMID 28542422, 2017). "Whilst women with depressive symptoms had significantly higher risk factors associated with diabetes (central obesity levels, IR, leptin and TNF-α), depression in men was associated with higher levels of CRP which potentially suggests an increased risk of CVD." (PMID 29190710, 2017). "Inflammatory cytokines such as TNF-α, IL-6, and IL-1β can cause adipocyte dysfunction, which is involved in the development of diabetes." (PMID 27878229, 2016). "Lastly, the robustness of hubs was determined by challenging islets with cytokine cocktails (IL-1β/IL-6 or IL-1β/TNF-α) to re-create the pro-inflammatory milieu thought to be associated with diabetes." (PMID 27452146, 2016). "The inflammatory process in diabetes is associated with the secretion of inflammatory cytokines by endothelial cells, e.g., tumor necrosis factor-alpha (TNF-α) and interleukin 6 (IL-6)." (PMID 26861982, 2016). "The overproduction of TNF-α is linked to the development of various diseases such as asthma, RA, psoriatic arthritis, inflammatory bowel disease, septic shock, diabetes, and atherosclerosis." (PMID 27881135, 2016). "A surge in pro-inflammatory markers, Il-6 and TNF-α, has been associated with type 2 diabetes mellitus (T2DM)." (PMID 26391589, 2015). "After 10 weeks of feeding, the elevated plasma glucose, TNF-α, and IL-6 and lower adiponectin levels caused by diabetes were effectively reversed by chitosan treatment." (PMID 25871293, 2015). "TNF-α is produced mainly by monocytes/macrophages and is associated with increasing vascular endothelial permeability in diabetes mellitus." (PMID 26207369, 2015). "Proinflammatory chemokines and cytokines like macrophage chemotactic protein (MCP-1), tumor necrosis factor (TNF-α), and interleukins (IL-1β and 6) have been recently implicated in the progression of diabetes to diabetic complications." (PMID 25821809, 2015). "The intravitreal injection of an inhibitor of TNF-α leads to a significant reduction in the loss of pericytes and capillary degeneration in diabetic mice, and TNF-α-deficient mice show decreased vascular changes induced by diabetes." (PMID 26137497, 2015). "Histone modifications at the TNF promoter also associated with the disease states of diabetes and systemic lupus erythematosus." (PMID 26406892, 2015). "In contrast, patients with ischemic stroke or diabetes have been recognized to show higher plasma concentrations of TNF-α, which is caused by elevated inflammation." (PMID 26665003, 2015). "NF-κB regulates the expression of enzymes (such as COX-2 and iNOS), cytokines (such as TNF, IL-1, IL-6, IL-8), adhesion molecules and has been linked with age-related diseases such as atherosclerosis, diabetes, osteoporosis, Alzheimer’s disease, and cancer." (PMID 25871293, 2015). "It is the production of inflammatory cytokines (IL-1 and TNF) that contribute to the loss of insulin producing β-cells and diabetes development." (PMID 26295266, 2015). "Deregulation of TNF-α has been implicated in the pathogenesis of numerous complex diseases, including periodontitis, cardiovascular diseases, diabetes mellitus, autoimmune diseases, and cancer." (PMID 25179218, 2014). "Diabetes mellitus type 1 (DM1) is associated with defects in TNF-α signaling which result in an altered balance between TNF's prosurvival and proapoptotic effects." (PMID 25053869, 2014).
diabetes (continued). "Cytokines such as IL-6, IL-1β, and TNF-α are known for their involvement in the process of bone loss in diabetes." (PMID 24803925, 2014). "Patients with diabetes often have elevated plasma levels of TNFα and LPS both of which are associated with an increased risk of ASCVD." (PMID 24835252, 2014). "The risk is increased in patients with cirrhosis, HIV, diabetes mellitus, malignancy, following treatment with anti-tumor necrosis factor and peritoneal dialysis." (PMID 24382008, 2014). "Patients with diabetes have increased plasma levels of TNFα and LPS both of which have been linked to increased cardiovascular disease risk and the induction of inflammatory responses in endothelial cells." (PMID 24835252, 2014). "The use of disease-modifying antirheumatic drugs (DMRADs) such as hydroxychloroquine or tumor necrosis factor inhibitor for lowering the inflammatory response in patients with RA has been shown to reduce the risk of developing diabetes." (PMID 24988532, 2014). "For example, NF-κB activation in the DRG was reduced in TNF-α knock-out mice protected from STZ-diabetes-associated reductions in motor NCV and thermal hypoalgesia." (PMID 25329046, 2014). "The upregulation of pathogenic factors, such as VEGF and TNF-α, has been reported during diabetes-induced microvasular dysfunction." (PMID 25356875, 2014). "Recently, a number of candidate-gene studies for diabetes in Han Chinese population have been reported, and the association between TNF-α −308G>A (rs1800629) and T2DM is a hot focus." (PMID 23527193, 2013). "Diabetes was confirmed by hyperglycemia and elevated glycated haemoglobin (HbA1c%), which were associated by weight loss, elevated tumor necrosis factor (TNF)-α and decreased insulin growth factor (IGF)-1β in the serum." (PMID 23840309, 2013). "We assess the level of tumour necrosis factor alpha (TNF-alpha) in tear fluids and other serumparameters associated with diabetes in different degrees of diabetic retinopathy." (PMID 24259948, 2013). "The pooled OR (95% CI) for TNF-α −308G>A under the dominant model (GA+AA vs. GG genotype) was 1.47 (1.17–1.85), also interpreted to be a modest-size risk of diabetes." (PMID 23527193, 2013). "A meta-analysis was applied to evaluate the associations between tumor necrosis factor-α (TNF-α) −308G>A (rs1800629) polymorphism and type 2 diabetes mellitus (T2DM)." (PMID 23527193, 2013). "In PLNs and fat, TNF-α interacted with 53% and 32% of genes, respectively, associated with reversal of diabetes by previous treatments and was thereby selected as a therapeutic target." (PMID 22606220, 2012). "Even after adjusted for compounding factors like TNF-α, IL-6, and leptin, adiponectin stood as independent marker of association with genetic predisposition for future development of diabetes (P < 0.01)." (PMID 23213322, 2012). "In PLNs and fat TNF-α interacted with 53% and 32% of genes, respectively, associated with reversal of diabetes by previous treatments." (PMID 22606220, 2012). "TNF-α production is thought to play a role in the generation of microvascular complications associated with diabetes, e.g., by enhancing chronic eye inflammation." (PMID 22500980, 2012). "TNF a increases MTP, and we found MTP to be increased in animal and human diabetes, a condition that is associated with increased TNFa." (PMID 22007304, 2012). "Accumulation of intracellular sorbitol can result in an increased intracellular osmotic pressure and activation of cytokines such as TNF leading to some of the pathophysiological changes associated with diabetes." (PMID 24250489, 2012). "For diabetes, our previous study found that TNF 308 G/A polymorphism as a risk factor for type 1 diabetes mellitus (T1DM)." (PMID 21494616, 2011). "Many investigations have focused the association between TNF 308 G/A polymorphism and risk for type 2 diabetes mellitus (T2DM)." (PMID 21494616, 2011).
diabetes (continued). "In ApoE−/− mice also deficient for TNFα, cholesterol levels were also increased by diabetes and this effect was more pronounced than in ApoE−/− mice." (PMID 20856927, 2010). "Specifically, TNF-alpha is a major pro-inflammatory cytokine produced from a variety of cells (e.g., monocytes, macrophages, endothelial cells, adipose tissue), and associated with many inflammatory diseases including diabetes and cardiovascular diseases." (PMID 40770283, 2025). "Some studies have demonstrated that increased levels of pro-inflammatory cytokine caused by diabetes (e.g., IL-6, TNF-α) inhibit muscle protein synthesis, promote protein degradation, and impair muscle function, which are inversely associated with muscle strength." (PMID 40354753, 2025). "This study found that TNF-α is positively associated with diabetes and negatively associated with male fertility parameters, including testosterone, testis weight, sperm motility, and sperm concentration, confirming the results of the meta-analysis and gene expression pathway analysis." (PMID 41334449, 2025). "MR studies have provided suggestive evidence that TNF is associated with risk of diabetes." (PMID 40937292, 2025). "For the AG genotype of TNF-α-238 G/A (rs361525), a higher risk for a family history of diabetes mellitus compared to other examined family histories was found [OR = 6.48, 95% confidential interval (CI) 0.7–59.6, p = 0.02, sensitivity 0.07, specificity 1.0, power test 0.289]." (PMID 40565595, 2025). "Furthermore, the risk of diabetes mellitus in AS patients appears to be lower when anti-TNF therapy is combined with hydroxychloroquine (HCQ)." (PMID 39649224, 2024). "The study of the association between TNF-α, diabetes, and oral cancer may point to theragnostic targets as well as biomarkers for diagnosis." (PMID 38406163, 2024). "Impaired fracture healing in diabetes may be caused by reduced MSCs proliferation and increased MSCs apoptosis that are enhanced by TNFα as shown in mice with streptozotocin-induced diabetes." (PMID 39796055, 2024). "Additionally, the levels of inflammatory biomarkers, including IL-6 and TNF-α, were found to be significantly higher in the saliva of diabetic patients, reflecting the tissue damage and systemic inflammation associated with diabetes." (PMID 39795606, 2024). "Considering the critical role of NF-κB in orchestrating the inflammatory response through the upregulation of pro-inflammatory genes, we sought to elucidate the intricate interplay between TNF-α, IL-6, and NF-κB in the context of diabetes-associated inflammation." (PMID 39496097, 2024). "TNF-α has been linked to the development of complications related to diabetes." (PMID 39273664, 2024). "We found that diabetes was associated with lower levels of TNF-α." (PMID 38459460, 2024). "Local high levels of TNF-α could activate FOXO1 in the process of endochondral ossification in patients with fractures associated with diabetes, leading to an increased mRNA expression level of apoptosis gene and chondrocyte apoptosis." (PMID 38713402, 2024). "Our study demonstrated that the administration of periodontal hydrogels containing carvacrol and magnolol in Wistar rats with periodontal disease associated with diabetes decreases the levels of IL-6 and TNF-α in gingival tissue, favoring a reduction in inflammation." (PMID 39062018, 2024). "Studies of diabetic animal models and human disease have demonstrated that diabetes is associated with persistent systemic inflammation due to increased secretion of pro-inflammatory cytokines, such as the tumor necrosis factor (TNF)-α, interleukin (IL)-1β, IL-6, and IL-18." (PMID 39563316, 2024). "The condition is linked to higher levels of IL-18, TNF-α, and IL-6, indicating inflammation that may drive type 2 Diabetes Mellitus (T2DM)." (PMID 40027364, 2024). "Based on our recent study TNFα causes the diabetes-related effects primarily through TNFR2." (PMID 36672637, 2023).